CD4 (CD4 molecule)
Diseases named in the same sentence as CD4 in open-access papers (continued):
Sharing a sentence is not in itself a finding about the gene and the disease.
breast cancer (969 papers, 2004 to 2026). A primary or metastatic malignant neoplasm involving the breast. "Resting CD4 memory cells are associated with overall survival in various cancers, including breast cancer, endometrial cancer, and CRC." (PMID 40699864, 2025). "In the SOLAR-1 phase II study (NCT03056755), patients with HR+/HER2− advanced breast cancer harboring PIK3CA mutations received alpelisib plus fulvestrant following CD4/6 inhibitor treatment with the aromatase inhibitor." (PMID 40142329, 2025). "The MR analysis showed evidence that genetically‐predicted lower expression of EIF5A expression in various CD4+ T cell subtypes was associated with increased risk of breast cancer (OR = 0.96, p = 1.7 × 10−3)." (PMID 41216857, 2025). "The association between the CD4RA gene pair terminally differentiated CD4+ lymphocyte ratio and breast cancer risk was estimated by MR analysis." (PMID 41088579, 2025). "As a result, we identified T-helper-inducing Poxviruses and Zinc-finger (POZ)/Krüppel-like factor (ThPOK, ZBTB7B), a CD4+ cell lineage commitment factor, as a breast cancer master regulator that is recurrently associated with a SE." (PMID 40235471, 2025). "TSLP-induced breast cancer suppression was associated with CD4+ T cell accumulation around breast cancer." (PMID 40873585, 2025). "V-domain Ig suppressor of T cell activation (VISTA; encoded by VSIR), a checkpoint molecule expressed on naive CD4+ T cells, Tregs, and myeloid cell subsets, plays a multifaceted role in the context of breast cancer." (PMID 41550427, 2025). "Intriguingly, the TIME of Ing4-deleted mouse mammary tumors consisted of increased tumor-associated macrophages (TAMs) and decreased GzmB+CD4+ T cells." (PMID 38968186, 2024). "Previous spatial transcriptomic analysis of breast cancer 23 showed that CD8+/CD4+ T-cell tumor infiltration was more frequently associated with iCAF populations than myCAF." (PMID 38505604, 2024). "Infiltration levels of CD4 memory T cells significantly decrease with increasing risk scores in breast cancer patients." (PMID 38312844, 2024). "Higher levels of CD8+ cytotoxic T cells and lower levels of CD4+ helper T cells are typically associated with a better prognosis and outcome in human breast cancer." (PMID 38397942, 2024). "Elevated MIF expression supported tumor growth while a loss of MIF promoted the anti-tumor immune infiltration of CD4 + /CD8 + T cells producing IFN in breast cancer." (PMID 38685050, 2024). "High densities of tumor‐associated macrophages, neutrophils, and CD4+ T cells have typically been associated with poor prognosis in breast cancer." (PMID 38193115, 2024). "In the analysis of different breast cancer therapies, radiotherapy was associated with decreases in percentages of total CD4+ T cells, and chemotherapy was associated with increases in percentages of naive B cells." (PMID 38358741, 2024). "Activin has been implicated in the promotion of a CD4+/Foxp3+ phenotype in a dose‐dependent manner in both malignant (breast cancer) and non‐cancerous disease models." (PMID 39248018, 2024). "In breast cancer survivor–only analyses, radiotherapy was associated with decreases in total CD4+ T cell levels, whereas chemotherapy was associated with increases in naive B cell levels." (PMID 38358741, 2024). "A report on breast cancer has demonstrated that an elevated level of resting and activated CD4 memory T cells is directly linked to greater disease-free survival." (PMID 37876593, 2023). "Several studies have also found that activated memory CD4 T cells are associated with prognoses in many cancers, such as breast cancer, cervical cancer, non-small cell lung cancer, and pancreatic adenocarcinomas." (PMID 37428291, 2023). "Compared to mice with single deficiencies in T cell PARP1 or PARP2, mice with PARP1/2 double deficiencies have faster proliferating breast cancer cells and reduced CD4+ and CD8+ T cell infiltration in tumor tissues." (PMID 38111536, 2023).
breast cancer (continued). "Polarization to Th2 phenotype of CD4+ T cells was evident in breast cancer patients in advanced stages and associated with the immunotherapy, prognosis and metastasis in luminal breast cancer." (PMID 38006403, 2023). "The same change of CD4+/CD8+ in TILs was also found to be associated with therapeutic response or tumor progression in breast cancer patients who received neoadjuvant chemotherapy." (PMID 35242718, 2022). "RYR2 is frequently mutated in breast cancer, and its mutations can enhance the infiltration of cytotoxic T lymphocytes, activate memory CD4+ T cells and M1 macrophages to enhance antitumor immune responses." (PMID 36176287, 2022). "The activities of the TGFβ, NFκB, PI3K-FOXO, JAK-STAT1/2, JAK-STAT3, and Notch STPs were measured in CD4+ T cell subsets and used to investigate cellular mechanisms underlying breast cancer-induced immunotolerance." (PMID 35158758, 2022). "In MBC patients receiving high-dose chemotherapy, high frequencies of mature CD14+HLA-DR+ monocytes, as well as specific subpopulations of CD8+ and CD4+ T lymphocytes, are associated with longer breast cancer-specific survival." (PMID 35626676, 2022). "The role of PD-1 on CD4+ Treg cells was strongly associated with high-risk prognostic factors in breast cancer patients, suggestive of synergistic contribution to impair the antitumor immune response." (PMID 35935577, 2022). "Clinical breast cancer samples with Piezo1 high expression had fewer immunogenic characteristics, including the reduction of the activated CD4+ memory T cells and CD8+ T cells, which was associated with poor prognosis in breast cancer patients." (PMID 36230880, 2022). "Lastly, IL-4-expressing CD4+ T cells were found to directly regulate tumor-associated macrophages (TAMs) in preclinical breast cancer models." (PMID 35335881, 2022). "Our results are also partially in line with a recent study reporting that high levels of distinct subpopulations of systemic CD8+ and CD4+ T lymphocytes associated with longer breast cancer-specific survival in MBC patients treated with high-dose chemotherapy." (PMID 35626676, 2022). "First, we found that TRIM8 gene copy numbers were inversely associated with the infiltration levels in breast cancer, including B cell, CD4+Tcell, and macrophage." (PMID 35368651, 2022). "CD4+ memory T cells (CD4+ MTCs) are closely associated with the prognosis in breast cancer, gastric cancer, lung adenocarcinoma, and pancreatic cancer, but the role in colon adenocarcinoma (COAD) is unclear." (PMID 36105107, 2022). "We also provide evidence that this change in the CD4+ T- cells is caused by a factor produced by breast cancer cells." (PMID 35158758, 2022). "A previous study revealed that Treg cells in human breast cancer are mainly derived from naïve CD4 + T cells recruited by tumor-associated macrophage-derived CCL18." (PMID 36221095, 2022). "In a study with 414 Danish patients with breast cancer showing gBRCA1/2 mutation, patients with gBRCA1 mutation had a higher rate of CD4+ cells than those with gBRCA2 mutation." (PMID 35462552, 2022). "Improved prognosis in human breast cancer is associated with CD4+ Tfh cells which produce an abundance of Cxcl13 and support B cell differentiation, TLS formation and GC maturation." (PMID 34122434, 2021). "High levels of all TIL subsets (except CD4) were significantly associated with breast cancer subtypes." (PMID 34076969, 2021). "Previous studies in breast cancer patients have shown that presence of cancer cells in the systemic circulation are associated with alteration of CD4+ TH cells." (PMID 34012451, 2021). "For the cells driven by CDH1, CD4+ central memory T cell (Tcm) was proposed to be negatively associated with recurrence-free survival in breast cancer." (PMID 34368166, 2021). "S100A8+ ICs were already present in early stage of breast cancer and were associated with increased CD4+, CD8+, FOXP3+ TILs and PD-L + ICs infiltration." (PMID 33146829, 2021).
breast cancer (continued). "In CD4+ T cell-deficient mouse mammary tumor models, pericyte coverage of blood vessels was reduced, and tumor tissue hypoxia was increased, suggesting that CD4+ T cell deficiency led to vascular abnormalities." (PMID 34294146, 2021). "In breast cancer, an elevated CD4/CD8 ratio has been associated with tumor progression and poor survival." (PMID 33653826, 2021). "TGFβ signaling in CD4+ T cells promotes a regulatory T cell phenotype, which has been associated with immunosuppression and poor prognosis in breast cancer." (PMID 34771508, 2021). "IL-4-expressing CD4+ T cells were previously shown to promote pulmonary metastasis of breast cancer by directly acting on tumor-associated macrophages, which enhance metastasis through activating epidermal growth factor receptor signaling in cancer cells." (PMID 34707103, 2021). "Ceruloplasmin expression was also associated with the infiltration levels of CD4+ T cells, neutrophils, and dendritic cells in basal-like breast cancer." (PMID 34413268, 2021). "The effectiveness of MicroCellClust is confirmed as it reveals a subpopulation of CD4 T cells with a specific phenotype from breast cancer samples, and a subpopulation linked to a specific stage in the cell cycle from breast cancer samples as well." (PMID 33830183, 2021). "Both human and mouse studies suggested the diversity and complexity of the source and function of CD4+CD25+ T cells associated with breast cancer." (PMID 33029539, 2020). "Increasing studies suggest that T cells CD4 memory activated are associated with improved prognosis, such as in pancreatic adenocarcinomas, breast cancer, cervical cancer, and non-small cell lung cancer." (PMID 33043974, 2020). "Although the association with CD4+ T cells was attenuated, we found that the near-term breast cancer associations for CD8+ T cell and monocyte subtypes remained unchanged (eTable 4 in the Supplement)." (PMID 31951276, 2020). "We therefore aimed to evaluate the relationships between prediagnostic erythrocyte membrane fatty acids and breast cancer risk by tumor tissue expression of immuno-inflammatory markers (CD4, CD8, CD20, CD163, COX-2) and fatty acid synthase (FAS)." (PMID 32698885, 2020). "We demonstrate its utility using breast cancer cell lines and patient samples to identify functional subtypes associated with specific drug responses (including CD4/6 inhibitor) and prognosis." (PMID 33007815, 2020). "Previous studies on breast cancer reported that lower ratio of CD8+/CD4+ is associated with poor prognosis, which is consistent with our findings." (PMID 32974156, 2020). "In contrast, there have been a few reports examining the role of CD4 + TILs in breast cancers; they were associated with more aggressive behavior." (PMID 32222891, 2020). "We therefore aimed to prospectively investigate the relationships between erythrocyte membrane fatty acid concentrations and subsequent breast cancer risk by tumor tissue expression of several immuno-inflammatory markers (CD4, CD8, CD20, CD163, COX-2) and FAS." (PMID 32698885, 2020). "CCL5 has been implicated in luminal type breast cancer by modulating the phenotype of CD4+ T cells and in ER-positive breast cancers by promoting macrophage influx." (PMID 31921621, 2019). "While ER-positive breast tumors with low grade are considered to have a relative good prognosis in breast cancer, within these low-grade tumors, we observed that high levels of CD4 or CD8 were associated with poor outcome (log-rank test; p < 0.0001)." (PMID 31391067, 2019). "There was an association for both B cell naïve and memory types in breast cancer, and T cell CD4 memory- activated cell types in lung adenocarcinoma, head and neck, and pancreas cancers." (PMID 31533728, 2019). "CD4+/PD-1+ or CD4+/PD-1− tumor-infiltrating lymphocytes showed diverse association with pathological features of breast cancer." (PMID 30069490, 2018).
breast cancer (continued). "First we were able to observe that involution associated murine mammary tumors possess fewer intratumoral T cells overall, with a specific decrease within the CD4+ T cell compartment of Foxp3+ T cells." (PMID 30285905, 2018). "CXCL13-positive CD4+ Tfh cells are associated with a high frequency of peritumoral tertiary lymphoid structures and generally favorable outcome in breast cancer." (PMID 29482642, 2018). "Recently, we have identified that a loss of anti-HER-2 CD4 Th1 in peripheral blood occurs during breast tumorigenesis and is dramatically diminished, even in Stage I breast cancers." (PMID 27766079, 2016). "This poor clinical outcome in breast cancers with Th17 cell accumulation was shown to be associated with the inhibition of CD4+ cell and CD8+ cell activation, thus limiting anti-tumor immune reactivity." (PMID 27453801, 2016). "In some tumor types including hepatocellular carcinoma and breast cancer, high levels of intratumoral Foxp3+CD4+ T cells have been associated with bad prognosis." (PMID 26604855, 2015). "In murine breast cancer models, IL-4 secretion by CD4+ Th2 cells activate tumor-associated macrophages (TAM) to facilitate pulmonary metastasis mediated by secretion of EGF." (PMID 25208941, 2014). "Enhanced tumor growth in both carcinogen-induced fibrosarcoma and oncogene-driven mammary carcinoma was associated with decreased interferon-γ production by CD4 and CD8 T cells and increased numbers of regulatory T-cells (Treg)." (PMID 23554861, 2013). "In addition, CD45RA- CD4+ %CD4+ was also proven to be significantly linked with a decreased risk of breast cancer." (PMID 38327747, 2024). "Taken together, the study results present a novel mechanism of ING4-driven tumor-immune modulation and may offer potential opportunities for therapeutic intervention harnessing CD4 CTLs in ING4-deficient breast cancer." (PMID 38968186, 2024). "In particular, in in vivo experiments, the peptide enhanced the antitumor effect of DOX through the combination of IND, decreased IL‐6 expression, increased CRT and CD4 levels, attenuated tumor‐associated inflammation, and enhanced immunity, which effectively inhibited breast cancer growth." (PMID 39545088, 2024). "However, in a mouse model of mammary cancer, mutations in ERβ resulted in reduced infiltration of CD4+ and CD8+ T cells and lower levels of IFNγ within the tumor microenvironment, leading to tumor growth." (PMID 39682229, 2024). "Moreover, our study found that the infiltration of immune cells, such as γδT and CD4+ T cells, was associated with better clinical outcomes in breast cancer, which supports previous studies." (PMID 38982642, 2024). "Thanks to the rapid development of single-cell sequencing experiments and analytical techniques, some studies found that CD4+ conventional T cells-related lncRNAs signature was associated with hepatocellular carcinoma, breast cancer prognosis, therapy, and tumor microenvironment." (PMID 37063862, 2023). "In addition, our study found that SGPP1 expression in breast cancer was associated with neutrophils, macrophages, CD4+ and CD8+ cells." (PMID 37521466, 2023). "Our results also indicated that chemoradiotherapy resistance of breast cancer may be associated with the tumor immune cell infiltration, especially M1 macrophages, T-cell CD4 memory resting, and M2 macrophages." (PMID 36896338, 2023). "Similarly, a tri-specific antibody targeting HER2, CD3 and CD28 has caused regression of breast cancers in a humanized mouse model through CD4-dependent inhibition of tumor cell cycle progression." (PMID 37007133, 2023). "Furthermore, IL15RA and IL2RA are predicted to be targeted by several breast-cancer associated SNPs in cd19 and cd4 primary cells, as well as in vHMEC." (PMID 37428809, 2023). "Besides, the SKA3 expression level was associate with infiltrating levels of activated CD4 T cells and eosinophils in breast cancer." (PMID 34993016, 2021).
breast cancer (continued). "Inclusion of more-specific leukocyte subtypes, including regulatory T cells (a subset of CD4+ T cells) that are often found in the tumor microenvironment, may provide additional insights into the interplay of the immune system and breast cancer risk." (PMID 31951276, 2020). "In addition, a mechanistic explanation for the differential association between MUFAs and breast cancer risk by CD4/CD8 ratio remains to be elucidated." (PMID 32698885, 2020). "High CD4/CD8 ratios in breast cancer patients were strongly associated with worse prognosis." (PMID 29755647, 2018). "There is evidence of a loss of anti-HER-3 CD4 Th1 responses in triple negative and ER positive breast cancer suggesting loss of anti-oncodriver Th1 responses may be a broader defect than just that occurring in HER-2 tumorigenesis (Fracol manuscript accepted)." (PMID 27766079, 2016). "Recent data also support a more complex functional role of CD4 cells in breast cancer than considered before: extensive lymphocytic infiltration of breast cancer has been linked to increased CD4+ Th1 and Tfh populations, and is associated with better survival and higher pCR rates." (PMID 25432519, 2014). "Therefore, we aimed to assess whether the elevated levels of miR-19a-3p in the serum of patients with metastatic HER2 + breast cancer and a favorable prognosis were associated with the levels of CD4 + T cells expressing IFN-γ in the peripheral blood." (PMID 41582199, 2026). "Although long-term HIIT improves T cell function, it may exacerbate immune aging in certain populations, such as older women at high risk for breast cancer, leading to a decrease in CD4+ T cell counts and a lower CD4/CD8 ratio, suggesting that HIIT may promote immune aging." (PMID 40777031, 2025). "Notably, a study has found RNase1 might activate CD4+ T cells to inhibit breast cancer growth, while another has indicated it causes immunosuppression in liver cancer." (PMID 39932384, 2025). "To further evaluate whether IL-24 induction by calcipotriol was linked to CD4+ T cell infiltration in mammary tumors, we assessed the colocalization of IL-24–expressing cells with CD4+ T cells in PyMt tumors of WT mice treated with EtOH, calcipotriol, or calcipotriol plus anti-CD4 Ab." (PMID 39782693, 2025). "Niemiro and colleagues observed a reduction in CD4+ T-cell numbers following a 12-week exercise high-intensity interval exercise intervention (n = 8) compared with a moderate-intensity exercise intervention (n = 8) and usual care (n = 8) in older women at high risk of breast cancer." (PMID 39703835, 2024). "In addition to its essential role in polarization of TSLP-stimulated CD4+ T cells, we find that baseline IL-4/13 signaling, which is also implicated in normal mammary gland development, can protect against breast cancer development." (PMID 35657353, 2022). "Using Philips signaling pathway analysis, we provided evidence that soluble factors in primary breast cancer tissue induce an immune-tolerant CD4+ T cell state, likely caused by activated immune-suppressive Treg cells that may already be detectable in blood samples." (PMID 35158758, 2022). "Tfh is a CD4 T helper subset (T follicular helper) was recently found to correlate with improved survival when increased in tumors and, along with B cells, can mediate the response to checkpoint inhibitors in mouse models of augmented mutation burden in breast cancer." (PMID 34209203, 2021). "Indeed, previous studies showed that activation of the leptin/ObR axis can result in a chronic inflammatory status, a well-known risk factor for breast cancer, with leptin being involved in CD4+ T-regulatory cells differentiation due to ObR overexpression on lymphocyte plasm membrane." (PMID 33644151, 2021).